GNAQ (G protein subunit alpha q)
Diseases named in the same sentence as GNAQ in open-access papers (continued):
Sharing a sentence is not in itself a finding about the gene and the disease.
benign vascular tumor (2 papers, 2021 to 2025). "Frequent activating hotspot mutations in GNA genes, including GNA14 Q205, GNA11 and GNAQ Q209 were identified in 16 of 64 benign vascular tumors (25%)." (PMID 34040639, 2021). "Recent molecular studies have suggested that AH harbors activating mutations in the GNAQ gene, similar to other benign vascular tumors but absent in AS." (PMID 40364141, 2025).
bladder cancer (2 papers, 2022). "The network analysis revealed that GNAQ, NTRK3, and IKZF1 are related to UC because they are involved in PI3K/AKT and bladder cancer signaling." (PMID 35864526, 2022).
esophageal adenocarcinoma (2 papers, 2022 to 2025). A malignant tumor with glandular differentiation arising predominantly from Barrett mucosa in the lower third of the esophagus. "An oncogenic, canonical GNAQ-NTRK2 fusion identified in a patient with esophageal adenocarcinoma patient would have likely been missed as breakpoints within both genes were in intronic regions (intron 1 of GNAQ, intron 15 of NTRK2) that are not typically covered in DNA-only hybrid capture panels." (PMID 40385986, 2025).
hepatocellular carcinoma (2 papers, 2021 to 2024). A malignant tumor that arises from hepatocytes. "The molecular cause of this process is unknown but could be related to nonreceptor site binding/activation of G protein subunit alpha q (GNAQ) or other impacts on epidermal growth factor receptor (EGFR), Src, and tyrosine kinase expressed in hepatocellular carcinoma (TEC) family kinases." (PMID 39345278, 2024).
lung adenocarcinoma (2 papers, 2018 to 2023). A carcinoma that arises from the lung and is characterized by the presence of malignant glandular epithelial cells. "Our in silco analysis showed a significant correlation between GNAQ and ZO-1/2 expression in both lung adenocarcinoma and squamous cell carcinoma, suggesting that GNAQ is a potent upstream regulator of these two proteins." (PMID 37240145, 2023).
Parkinson (2 papers, 2019 to 2024). "We also found that GNAQ, GRIN1, and PLCB1 are in both Huntington's and AD but not in Parkinson's pathways, and SNCA is in both Parkinson's and AD but not Huntington's pathways." (PMID 31068785, 2019).
phakomatosis pigmentovascularis (2 papers, 2016 to 2024). "Here, we discover that extensive dermal melanocytosis and phakomatosis pigmentovascularis are associated with activating mutations in GNA11 and GNAQ, genes that encode Gα subunits of heterotrimeric G proteins." (PMID 26778290, 2016).
Sepsis (2 papers, 2016 to 2025). Sepsis is defined as life-threatening organ dysfunction caused by a dysregulated host response to infection. "qRT-PCR validation demonstrated significantly elevated expression of TGFA (P = .0306), GNAQ (P = .0185), and PDSS1 (P = .0052) in septicemia patients." (PMID 41305715, 2025).
adrenal tumors (1 paper, 2022). "Somatic mutations that constitutively activate WNT/β-catenin (CTNNB1), G-protein (GNAS, GNAQ, GNA11), and cAMP/protein kinase A (PKA) (GNAS, PRKACA) signaling can drive unrestrained cell proliferation and survival in diverse tumors, including adrenal tumors." (PMID 36004349, 2022).
arteriovenous malformations (1 paper, 2022). "The etiology of CCT is associated with a mutation of the GNAQ gene, the RASA1 gene, or the MAP2K1 gene.Mutations of the latter two genes are associated with the coexistence of CCT and arteriovenous malformations (AVMs)." (PMID 36013378, 2022).
B-cell lymphoma (1 paper, 2021). "We identified 666 mutations from 262 genes in baseline cfDNAs from 79 B-cell lymphoma patients, and found some genes were preferentially mutated in our cohort such as GNAQ, GNAS, H3F3A, DNMT3A, HLA-A, and HLA-B." (PMID 34926267, 2021).
bone tumors (1 paper, 2023). "In bone tumors, the MSKCC cohort had significantly fewer mutations in MAP3K1, CREBBP, MCL1, GNAQ, MEF2B, MYCN, SDHA, and SMARCA4." (PMID 37546405, 2023).
brain tumor (1 paper, 2024). "CNV events affecting these three likely pathogenic mutations, GNAQ R183Q, S1PR3 G89S, and NRAS G12V, were observed exclusively in abdominal and brain tumor samples and not detected in the cerebral cortex, white matter, or skin." (PMID 38254245, 2024).
choroidal melanoma (1 paper, 2015). Malignant tumor of melanocytes of the choroid. "We report that the GNAQ Q209P mutation is almost exclusively detected in choroidal melanoma that originate from the posterior region." (PMID 26368812, 2015). "We propose that light-induced damage may underlie the almost exclusive presence of the GNAQ Q209P mutation in choroidal melanoma." (PMID 26368812, 2015).
coronary artery stenosis (1 paper, 2023). "Therefore, increased expression of Gαq associated with the TT/TT genotype of GNAQ may initiate coronary artery constriction, predisposing the patient to coronary artery stenosis requiring stent insertion and to severe cardiovascular events, as shown in our analysis of TT/TT genotype carriers." (PMID 37894940, 2023).
desmoid tumor (1 paper, 2022). A desmoid tumor (DT) is a benign, locally invasive soft tissue tumor associated with a high recurrence rate but with no metastatic potential. "We found that desmoid tumors harbor mutations in CTNNB1, APC, and GNAQ, all of which are associated with pathological activities." (PMID 36497457, 2022). "In summary, this study demonstrated that fibroblasts, T-cells, and macrophages in desmoid tumors may have an increased response to TGF-β, and that the TGF-β signaling pathway may crosstalk with the Wnt and GNAQ pathways." (PMID 36497457, 2022).
DiGeorge syndrome (1 paper, 2024). "Most cases are sporadic but rare cases have been described in neurofibromatosis type 1 (NF1), Down syndrome (trisomy 21), DiGeorge syndrome (22q11.2 deletion syndrome), Sturge-Weber syndrome (somatic GNAQ variants) and familial melanoma-astrocytoma syndrome (CDKN2A/B loss)." (PMID 39294363, 2024).
esophageal carcinoma (1 paper, 2021). A primary or metastatic malignant neoplasm involving the esophagus. "In this study, we found that the expression of GNAQ in esophageal carcinoma and EA was lower than normal." (PMID 34124063, 2021).
glaucoma (1 paper, 2024). Increased pressure in the eyeball due to obstruction of the outflow of aqueous humor. "One had microdeletion 22q11.2 and microcephaly; in the other patient with TOF and extracardiac anomalies (microtia, glaucoma, nevus flammeus, supratentorial angioma), genetic testing revealed a GNAQ mutation." (PMID 38337754, 2024).
immune deficiency (1 paper, 2025). "Through differential analysis, three key genes – GNAQ, ELP3, and TES – were identified as closely linked to processes related to ribosome biogenesis, DNA replication, and congenital immune deficiency." (PMID 39925840, 2025).
Infertility (1 paper, 2024). "Some of the genes presented, such as CCSER1, GNAQ, NCOA2, SNRK, and TSPO, have been previously associated with fertility traits in livestock species or related to infertility in human patients (CEP78 and GPER1)." (PMID 38540441, 2024).
inflammatory bone disorders (1 paper, 2022). "Enhanced expression of GNAQ at the site of inflammation in RA patients indicates its pathophysiological relevance in the context of inflammatory bone disorders." (PMID 36699722, 2022).
ischemic stroke (1 paper, 2024). A stroke disorder caused by obstruction of blood flow to the brain, due to thrombotic (local blood clot formation) or embolic (due to a blood clot or other material traveling from another site) event. "DEPs, including GNAQ (G protein subunit α Q), CA3 (carbonic anhydrase 3), ARL6IP5 (ADP ribosylation factor like GTPase 6 interacting protein 5), and SPTB (spectrin β) were identified in total participants between recurrence and nonrecurrence patients with ischemic stroke." (PMID 38420847, 2024).
liver cancer (1 paper, 2021). An epithelial or non-epithelial malignant neoplasm that arises from the liver. "Since carcinogenic phenotypes such as growth and migration are not necessarily positively correlated, the role of wild-type GNAQ in liver cancer warrants further investigation using more cells and patients." (PMID 33807071, 2021).
melanotic schwannoma (1 paper, 2020). "Other diagnostic approaches include the recent molecular study of GNAQ gene mutations, which permit highly accurate discrimination between leptomeningeal melanocytic lesions and melanotic schwannoma." (PMID 32011473, 2020).
neurofibroma (1 paper, 2025). An intraneural or extraneural neoplasm arising from nerve tissues and neural sheaths. "In addition, our mouse model provides important evidence that oncogenic GNAQ in postnatal Plp1-expressing cells causes nerve sheath–like neoplasms, which should be further investigated as oncogenic hotspot mutations in GNAQ have now been found in plexiform neurofibromas and MMNSTs." (PMID 39804140, 2025). "Given the strong similarity between neurofibromas and mouse sparse pigment tumors, combined with the fact that GNAQQ209L alone was able to stimulate their formation, we investigated the cBioPortal for Cancer Genomics database to search for mutations in GNAQ or GNA11." (PMID 39804140, 2025).
skin tumors (1 paper, 2025). "On the other hand, skin tumors were enriched for the certain arms of the GNAQ signaling cascade, namely PI3K/AKT/MTOR signaling and RHO GTPases activating formins." (PMID 40950146, 2025).
tuberous sclerosis (1 paper, 2019). Hereditary disease characterized by seizures, intellectual disability, developmental delay, and skin and ocular lesions. "Indications of an increased risk were found for de novo tuberous sclerosis and Sturge–Weber syndrome, which suggest that maternal smoking during pregnancy might affect mutagenesis in TSC1, TSC2, and GNAQ." (PMID 31564984, 2019).
uveal tumours (1 paper, 2016). "In addition, recent findings demonstrated the activation of transcription factor YAP in UM by GNAQ/11 oncogenes and highlighted its fundamental role in the maintenance of uveal tumours." (PMID 27166257, 2016).
tumor (108 papers, 2012 to 2026). "GNAQ mutations were associated with Class 1 tumors (p < 0.0001), decreased patient age (p = 0.008), decreased tumor diameter (p = 0.003) and tumor thickness (p = 0.0006)." (PMID 41387680, 2025). "Co-occurrence of different GNAQ mutations within the same tumor, while rare, has been previously reported." (PMID 40461505, 2025). "The GNAQ gene mutations result in an overactive protein, which leads to an excessive signaling, that contributes to cells overgrowth and tumor formation." (PMID 38175637, 2024). "All seven tumours contained a hotspot variant in either GNAQ (two tumours) or GNA11 (five tumours), consistent with somatic variants in these genes being common initiating events in UMs." (PMID 39766052, 2024). "The mutant allele abundance increased with tumor progression, while an increase in the wild-type allele frequency has been observed in UM tumors with mutations in GNAQ, GNA11 or PLCB4, indicating a complex relationship between these genetic alterations." (PMID 38920653, 2024). "Tumor‐specific GNAQ/GNA11 mutations in the cell‐free DNA were determined using deep amplicon sequencing and the proportion of mutant versus wild‐type sequences was used as a measure for the proportion of tumor‐derived DNA in the plasma of the patients." (PMID 34291585, 2021). "BAP1 mutations are thought to appear after the GNA11 or GNAQ mutations, correlating with a gratly increased risk for tumor progression." (PMID 33903674, 2021). "Whereas most tumours harbour a mutation in GNAQ or GNA11, CYSLTR2 (encoding G-protein coupled receptor CysLT2R) forms a rare alternative." (PMID 33588787, 2021). "Since there is no treatment given directly targeting GNAQ/GNA11 mutations, we believe it is less likely that the frequency and pattern of GNAQ/GNA11 mutations changed from the diagnosis of metastasis to the time of tumor specimen procurement in this study." (PMID 34830903, 2021). "These genes, encoding phospholipase C β4 and a Gαq-coupled receptor respectively, are typically mutated in GNAQ and GNA11 wild-type tumours, providing an alternative way of activating the Gαq signalling pathway." (PMID 33588787, 2021). "Previous analyses of cell‐free DNA from plasma had shown detectable levels of tumor‐specific GNAQ/GNA11 mutations in patients with the clinical diagnosis of progressive disease." (PMID 34291585, 2021). "This strongly suggests that GNAQ p.Gly48Leu is a possible tumor-activating driver mutation, consequently triggering the MEK pathway." (PMID 33126538, 2020). "Our analysis strongly suggests that GNAQ p.Gly48Leu is a tumor-driver mutation possibly activating Gαq." (PMID 33126538, 2020). "It is known that posterior UMs carry specific mutations: in 94% of all tumours, a mutation in either the GNAQ or GNA11 gene has been found." (PMID 32998469, 2020). "All but one tumour have a known UM driver gene mutation (GNAQ, GNA11, BAP1, PLCB4, CYSLTR2, SF3B1, EIF1AX)." (PMID 32415113, 2020). "An initial event, common to all tumor groups, is represented by GNAQ and GNA11 mutations, determining constitutive MAPK activation." (PMID 29156643, 2017). "In agreement with previous data illustrating that 83% of BNs and 50% of MABNs harbored GNAQ mutations, GNAQ was mutated in all of our tumor samples at a high frequency, thus confirming that GNAQ mutation is an initiating event." (PMID 27057633, 2016). "A comparable PFS improvement to that in the overall population was observed in patients with tumours harbouring a mutation in GNAQ or GNA11." (PMID 26059332, 2015). "UM is a rare tumor for which only recently the first step in the molecular etiology was revealed with the identification of GNAQ and GNA11 mutations." (PMID 26368812, 2015). "We found that this tumor bears a somatic glutamine 209 to proline substitution in GNAQ (GNAQQ209P), which is known to cause constitutive activity." (PMID 23555837, 2013).
tumor (continued). "Thus, this study explored DNA vaccination as a measure to educate the immune system to recognize the most common UM-associated Q209L tumor driver mutation in GNAQ and GNA11 G-alpha proteins." (PMID 41681951, 2026). "As a G protein α subunit, GNAQ mutations are associated with tumor development." (PMID 41305715, 2025). "PCR tests of tumor samples of other 2 patients revealed driver mutations in the GNAQ gene." (PMID 40406270, 2025). "The presence of a mutation in the GNAQ gene, a karyotype with a mosaic trisomy of chromosome 6, and a mosaic loss of chromosome Y may play a role in the malignancy grade of the tumor in older children." (PMID 40151649, 2024). "Also of interest are the actionable gene mutations acquired and found in tumor progression within nude mice, such as GNAQ, RAC1, and SF3B1." (PMID 37108696, 2023). "Recent research proposed that the pathway based on the axis GNAQ/11–PLCβ–PKC–MAPK could be a preferential target in the treatment of tumours with underlying Gαq pathway mutations, such as most of the UM cases." (PMID 35008260, 2021). "Assessment of known UM driver genes revealed an oncogenic driver mutation in 102 of 103 tumours: 51 in GNAQ (48 p.Q209P/L, two p.R183Q, one p.G48L), 46 in GNA11 (44 p.Q209L/P, two p.R183C), five in PLCB4 (three p.D630Y, two p.D630N) and two in CYSLTR2 (p.L129Q)." (PMID 32415113, 2020). "It appears that the GNAQ mutation spectrum in this tumor is narrow, possibly restricted to p.Q209R." (PMID 31336681, 2019). "Of note, a commonality between mice and zebrafish genetically engineered UM models is the occurrence of melanocyte-derived neoplasms developing within the leptomeninges, which is consistent with the previously reported presence of GNAQ/11 mutations in human melanocytomas of the CNS." (PMID 27166257, 2016). "Increasing evidence has demonstrated that GNAQ is closely involved in tumour development and progression through multiple molecular mechanisms." (PMID 41362935, 2025). "The most frequent genetic mutations are in guanine nucleotide-binding protein alpha 11 (GNA11) and guanine nucleotide-binding protein q polypeptide (GNAQ), which are somatic in tumor cells." (PMID 40283643, 2025). "A Gαq signalling mutation at an established hotspot in GNAQ, GNA11, CYSLTR2 or PLCB4 is considered the primary driver event and is present in nearly all tumours." (PMID 40240901, 2025). "Lastly, the revelation of a tumor-suppressing miRNA that specifically targets GNAQ and AKT3 (miR-181a-5p) proved effective in hindering the progression of UM." (PMID 38920653, 2024). "These factors encompass chromosomal abnormalities, gene mutations (such as GNAQ and GNA11), gene expression profiles, tumor size, tumor location, and histopathological features." (PMID 38724687, 2024). "Mutations in GNAQ and GNA11 genes cause continuous activation of GPCR signaling, implicated in promoting cell growth, tumor cell invasion, and drug resistance in UM." (PMID 39061150, 2024). "Among the recurrently mutated genes, GNAQ and GNA11 are involved in the process of carcinogenesis and are mutated in 80–90% of these tumours." (PMID 35804836, 2022). "The results revealed that mutations in GNAQ, SEPTIN 6, NTRK3, and IKZF1 occur only in tumor samples." (PMID 35864526, 2022). "Analysis of tumour biopsies (n = 63) showed that 61 (97%) had likely loss of one copy of BAP1, 23 (37%) had mutations in the gene encoding GNAQ, 26 (41%) in GNA11, three (5%) in CYSLTR2, one (2%) in PLCB4 and 11 (17%) in SF3B1." (PMID 36229663, 2022). "Due to limited DNA concentration, four SCNA-positive AH samples (UM_005, 007, 012, and 013) were further evaluated for the presence of tumor variants in the BAP1 and GNAQ genes." (PMID 35682905, 2022). "Three cancer census genes, FOXO4 (NM_005938: p.S71C), GNAQ (NM_002072: p.T96S) and PDGFRB (NM_002609: p.V568E), acquire mutations as the tumor progresses to malignancy." (PMID 34816314, 2022).